ATM (ATM serine/threonine kinase)
Diseases named in the same sentence as ATM in open-access papers (continued):
Sharing a sentence is not in itself a finding about the gene and the disease.
cancer (continued). "Although ATM has been extensively studied in DNA damage repair and cancer biology, little is known about the specific contribution of non-coding RNAs to A-T pathogenesis." (PMID 41065894, 2025). "Approximately 11% to 17% of patients with metastatic PCa have been reported to have germline mutations in key hereditary cancer genes, including BRCA2, ATM, CHEK2, BRCA1, RAD51D, or PALB2, which represents a substantial population burden." (PMID 41086012, 2025). "Past studies have used the ATM inhibitor KU55933 both in vitro and in vivo to inhibit ATM signaling in cancers." (PMID 41366830, 2025). "The increase in ATM signalling promotes cancer cell survival, metastasis, and resistance to cancer therapies." (PMID 40282554, 2025). "Germline pathogenic or likely pathogenic variants in BRCA1, BRCA2, ATM, PALB2, and CHEK2 were identified across all four cancer types." (PMID 40361359, 2025). "A retrospective case–control study used data on 150,962 women tested with a multigene hereditary cancer panel to evaluate an 86-SNV PRS in BRCA1, BRCA2, CHEK2, ATM, and PALB2 P/LP variant carriers." (PMID 39858629, 2025). "The mechanistic study revealed that by triggering the ataxia telangiectasia mutated (ATM) pathway, xanthohumol exhibited its anti-cancer potential." (PMID 40599794, 2025). "Weaknesses in cancer cells that present DNA repair deficiencies or genomic instability can be exploited for synthetic lethality with Chk1/ATR and Chk2/ATM inhibitors." (PMID 40422251, 2025). "Analysis of the isolated tumors revealed that a loss of ATM accelerated PDAC progression and was associated with enhanced cancer cell stemness and EMT." (PMID 41155399, 2025). "Preclinical studies have shown that cancer cells made radioresistant through repeated irradiation evolve higher ATM levels and faster DNA repair kinetics." (PMID 40725389, 2025). "Medicinal chemists have made significant strides in leveraging key biological discoveries about the roles of DNA-PK, ATR, and ATM in the initiation and progression of cancer to design tractable chemical architectures exerting their modulation." (PMID 40256842, 2025). "Some other genes, like CHEK2, ATM, PALB2, and BRIP1, show a modest tendency for BC; however, patients with these genes' mutations have 2–3 times the high risk of developing a malignant tumor." (PMID 40755497, 2025). "These and other published results exemplify the opportunity to discover novel cancer vulnerabilities by pharmacological combinations targeting ATM, ATR and Chk1/2, especially in DDR impaired genetic backgrounds." (PMID 40422251, 2025). "Here, ATM inhibitors have been systematically categorised based on their structural frameworks and pharmacological activity for therapeutic applications in cancer." (PMID 40256842, 2025). "Apart from the canonical DDR exhibited by ATM and ATR, these factors have been extensively linked to nuclear envelope integrity, regulation of lamins and mechanosensitivity during cancer migration and invasion." (PMID 40923769, 2025).
cancer (continued). "Despite its established role as a tumour-down regulator, ATM’s contribution to cancer biology is nuanced, reflecting both protective and tumour-promoting effects." (PMID 40256842, 2025). "The data supports that APAP can elicit DNA DSBs and a subsequent ATM/Chk2 mediated DDR which is consistent with past studies using human carcinomas cells." (PMID 41366830, 2025). "In contrast, other DNA damage response and repair genes, including BRCA1, BRCA2, ATM, BRIP, POLQ, and CDK12, were significantly more often mutated in CDX2-suppressed cancers." (PMID 39452477, 2024). "The formalin fixed paraffin embedded samples of 48 cancer tissues were collected and stained to detect ATM protein expression." (PMID 38886866, 2024). "Although 58.3% of women with a mutation had several relatives with various types of cancer, segregation analysis was performed in some families with index cases having P/LP variants in BRCA2, ATM, and PALB2 genes." (PMID 38890714, 2024). "Until recently, the role of therapeutics targeting the DNA damage response such as PARP, ATR, DNA-PK and ATM for cancer treatment has largely focused on the tumor cells." (PMID 38402224, 2024). "While defects in ATM function are now recognized across these cancers, less is known about scenarios that depend on ATM activity- with potential for synthetic lethal targeting." (PMID 38347838, 2024). "This two-hit mechanism is common for deleterious germline variants in cancer predisposition genes, first discovered for RB118, and later shown for various other cancer risk genes including ATM and BRCA119." (PMID 39033140, 2024). "The mutation frequencies in BRAF, TERT, RET, ATM and GGT1 were significantly higher in cancer tissues than benign nodules." (PMID 38886866, 2024). "For example, ATM and BRCA2/FANCD1 had the highest mutated rate in only 5 out of 15 and 4 out of 15 cancer types, respectively." (PMID 39421870, 2024). "This highlights the importance of ATM as a factor regulating genome stability and the cellular response to DNA damage, as well as its potential role in cancer pathogenesis." (PMID 38892180, 2024). "ATM is the key mobilizer of cellular reaction to DNA impairment; Sp1 can contribute to DNA restore response and regulate cancer through ATM-mediated phosphorylation." (PMID 39228402, 2024). "Cancer cells chronically adapted to pHe 6.5 revealed a significant increase in phospho-ATM and phospho-ATR together with higher phospho-CHK1 and phospho-CHK2 levels (vs. cells maintained at pHe 7.4)." (PMID 38366255, 2024). "PARPi has been explored in multiple cancer types for patients harboring CHEK and ATM mutations and the results have varied." (PMID 38898688, 2024). "Given the important role of ATM in DSB signaling and repair, ATM inhibition combination therapy is currently an attractive strategy for cancer therapy in various clinical trials." (PMID 38763973, 2024). "Knowledge that ATM regulates CD13 is important in the development of novel therapeutic strategies harnessing the role of CD13 in cancer angiogenesis." (PMID 38933336, 2024). "Here we consider rare variants in two genes, Checkpoint Kinase 2 (CHEK2) and Ataxia-Telangiectasia Mutated (ATM), that are included on many cancer gene panels." (PMID 39209703, 2024). "It was recently demonstrated that PRS created meaningful risk gradients among female carriers of PVs in cancer-predisposing genes other than BRCA, including ATM, CHEK2, PALB2, BARD1, BRIP1, CDH1, and NF1." (PMID 38339330, 2024).
cancer (continued). "The ATM protein is a key determinant of tumor radiation response for multiple types of cancer, plays a central role in mediating inflammatory signaling, and is essential in regulating DNA damage response and radioresistance." (PMID 38260227, 2024). "For example, ATM depletion makes cancer cells more sensitive to ATR inhibitors or DNA damage, which ensures high levels of IFN expression dependent on the cGAS–STING signaling pathway." (PMID 38630271, 2024). "ATM missense variants have a similar effect as BRCA1 mutations on cancer cells, sensitizing the cancer cells to platinum-derived drugs." (PMID 38674216, 2024). "Our work demonstrated ATM inhibition and loss to impair CD13 expression in cancer cell line SH-SY5Y, but also an AT cell line." (PMID 38933336, 2024). "By losing ATM in cancer cells, HR is undermined; therefore, when DNA is damaged, these cancer cells depend on the rest of the DDR pathway for repair." (PMID 38910895, 2024). "The G-quadruplex ligand 20A elicits global DNA damage and activates the ATM pathway in both cancer cells (HeLa) and xenograft mouse models." (PMID 38910895, 2024). "Our DNA-seq analysis of 76,639 pan-cancer samples identified 31 DDR/FA signaling genes, with ataxia-telangiectasia mutated (ATM) showing the highest mutation rate at 5%, followed by BRCA2/FANCD1 at 4%." (PMID 39421870, 2024). "While ATM is widely recognized as a tumor suppressor and plays a crucial role in DNA damage sensing and response, some cancer cells can exploit ATM activation to develop resistance to chemotherapy by activating ATM." (PMID 39008483, 2024). "In light of this, pharmacologic inhibitors of ATM are being explored as potential cancer treatments, especially in combination with DNA-damaging agents like chemotherapy and radiation." (PMID 38730598, 2024). "The overexpression of SPIN1 in cancer cells enhanced its binding to H3K9me3 and persistently promoted the activation of ATM-mediated DNA repair in cancer cells exposed to DNA-damaging drugs." (PMID 39090319, 2024). "BRCA1/2 genes carry critical functions in ataxia telangiectasia mutated (ATM) -mediated DNA double-strand break (DSB) repair pathway (ATM-Pathway) and their mutations are associated with predisposition to numerous cancer types." (PMID 38914566, 2024). "ATM and CHEK2 are included on many cancer gene panels used in family cancer clinics, and the risk estimates from these analyses can inform genetic counselling for carriers." (PMID 39209703, 2024). "Several signaling pathways were found in the PC3 cell line, including PI3K-AKT-mTOR, TNF-related weak inducer of apoptosis (TWEAK), DNA damage response (only ATM dependent) and senescence, and autophagy in cancer." (PMID 38564578, 2024). "Recommended guidelines for early detection and cancer risk reduction in women with PVs in moderate-penetrance risk genes increasing lifetime cumulative risk over 20%, including PALB2, ATM, and CHEK2, are starting to become available." (PMID 38339330, 2024). "We also observed that ATM and BRCA2/FANCD1 consistently exhibit the highest mutation rates across different tissue-specific cancer types, a pattern corroborated by other mutational screening studies." (PMID 39421870, 2024). "We found that the FLT3LG exGS was largely explained by trans-pQTL that lie in established cancer risk genes involved in the regulation of cell division and DNA repair (CHEK2 [22:28695868:AG:A], ATM [11:108267276:T:C], and TERT [5:1293971:C:T])." (PMID 38750076, 2024). "Yet this topic remains complex as targeted inhibition of the ATM pathway has yielded positive effects via chemotherapy sensitization or synthetic lethality in certain cancers, illustrating the double-edged nature of DNA repair in tumor progression." (PMID 39095874, 2024).
cancer (continued). "Previous studies have shown that the activation of ATM in cancer cells induces autophagy through the phosphorylation of BNIP3 (Interacting protein 3)." (PMID 39000057, 2024). "The alterations in cancer susceptible genes such as BRCA1, BRCA2, PALB2, STK11, PRSS1, and ATM have been linked to increased lifetime risks of PDAC." (PMID 38350919, 2024). "APE1 was also shown to modulate the ATM-Chk2 DDR pathway activated by DNA alkylation damage in cultured human cancer HeLa cells, likely due to the generation of SSBs from AP sites by APE1’s AP endonuclease activity." (PMID 39112456, 2024). "Mutations in the ATM gene, located in the chromosomal region 11q22-23, may lead to conformational changes, inactivation of the kinase domain, or changes in the stability of the molecule, which may weaken the function of this gene and increase the risk of cancers." (PMID 38892180, 2024). "ATM is inactivated in approximately 5% of all cancers but is estimated to be inactivated in a larger proportion of mantle cell lymphomas and colorectal and uterine cancers." (PMID 38730598, 2024). "Due to their significant role in numerous cellular mechanisms closely associated with cancers, HSPGs, such as SDC4, and HSPG-related genes such as AKT1 and ATM present an exciting target for BC diagnostics and macromolecular drug therapies." (PMID 36152082, 2023). "The loss of PALB2, FANCA, BRIP1, and RAD51B were associated with improved responses, while responses were limited in ATM-, CHEK2-, and CDK12-deficient cancers." (PMID 38201511, 2023). "As upstream regulators of these cyclins and CDKs, ATM, ATR, CHK1, and CHK2 are among the most common cell cycle dysregulation events that promote cancer susceptibility across cancer types." (PMID 37390209, 2023). "Concordant with this, the key kinase genes in DSB repair, ATM and ATR, are frequently mutated in various human cancers." (PMID 37373360, 2023). "Although numerically higher response rates were seen in cancers with low ATM protein, the benefit seen in these patients were possibly lower than that observed with other ATR inhibitors or in preclinical models given in a more continuous schedule." (PMID 37773077, 2023). "Together, the findings of this study confirm the earlier reports establishing the fact that MST-312 acts through the activation of the ATM/pH2AX DNA damage pathway in short-term treatments of cancer cells." (PMID 38765717, 2023). "MSAI was observed on chromosome arms 11q (containing a number of cancer genes including ATM and KMT2A) and 12p, suggestive of ongoing clonal evolution and potential selection of SCNAs during treatment in this patient." (PMID 37081523, 2023). "ATR is important for cell survival, particularly in the context of ATM mutations, making ATR a prospective target for cancer treatment." (PMID 36902170, 2023). "It is noteworthy that cells and organisms survive with mutations in ATM or other components required for HRR, such as BRCA1 and BRCA2, but at the expense of genomic instability and cancer predisposition." (PMID 37627523, 2023). "A deficiency in ATM or its low expression is a biomarker of sensitivity to PARP or ATR inhibitors in cancer and the ATM-selective inhibitor AZD-1390 is currently in clinical trials." (PMID 37637936, 2023). "Acting as an effector of ATM (Ataxia telangiectasia mutated), G6PD often participates in the development of various cancers through metabolic programming and DNA repair pathways." (PMID 38098504, 2023).
cancer (continued). "Ionizing radiation-induced DNA double-strand breaks (DSBs) increased the expression of SERPINE1 in cancer cells in an ATM/ATR-dependent manner, and promoted nuclear localization of SERPINE1 to facilitate DSB repair." (PMID 36681663, 2023). "Taken together, our data indicate that continuous ATM inhibition in irradiated cancer cells provides a strong enhancement of the inflammatory signaling and leads to elevated expression and secretion of multiple inflammatory cytokines/chemokines." (PMID 36656721, 2023). "More research is needed to determine the magnitude of the cancer risk related to a specific gene alteration and to advise patients who have a variant in the CHEK2 or ATM genes." (PMID 37239898, 2023). "ATM and ATR are two critical factors to regulate DNA damage response (DDR), and their mutations were frequently observed in different types of cancer, including non-small cell lung cancer (NSCLC)." (PMID 38041093, 2023). "The enzyme ataxia-telangiectasia mutated (ATM) kinase is a key mediator of DDR, and its inhibition has become an attractive therapeutic concept in cancer therapy for the sensitization of cancer cells to chemotherapeutic drugs." (PMID 36900267, 2023). "We further demonstrate that misalignment and mis-segregation during aberrant mitosis leads to pronounced micronucleation, a powerful mechanism for activation of cGAS/STING induced inflammatory signaling in irradiated cancer cells exposed to the ATM inhibitors." (PMID 36656721, 2023). "Taken together, ATM seems to have a much more complicated role than just serving as a tumor suppressor during the onset and progression of cancer." (PMID 36650267, 2023). "DDR-targeted therapies including ATM inhibitors have been shown to convert the “cold tumor” into “hot tumor” in some cancer types, through inducing cGAS/STING-mediated innate immunity." (PMID 36778120, 2023). "Cancer immunotherapy can be improved by activating the cGAS-STING pathway, which has been linked to the inhibition of ATM, ATR, CHK1, and PARP." (PMID 36831197, 2023). "The ISGs induced by ATM inhibition were correlated with survival in cancer patients who received ICB therapy." (PMID 37174688, 2023). "All men carrying BRCA1 or BRCA2 mutations should start cancer screening at the age of 40 with yearly PSA and consider the same in men with BRCA1, ATM, HOXB13, and DNA MMR mutations." (PMID 37021836, 2023). "In this study, we showed that ATM inhibition activated interferon signaling and induced interferon-stimulated genes (ISGs) in cisplatin-resistant and parent cancer cells." (PMID 37174688, 2023). "Regarding the differentiation of cancer cells, patients with low ATM expression had a higher tendency for the poorly differentiated type, but no statistical difference was observed." (PMID 37674118, 2023).